ZNF844 (zinc finger protein 844)
Description:
May be involved in transcriptional regulation.
Synonyms: FLJ14959
Tractability: PROTAC: ubiquitination databases record sites on it.
Gene: Protein-coding gene on chromosome 19 (12,064,731 to 12,081,565, forward strand). Ensembl gene ENSG00000223547.
Subcellular location: Nucleus
Gene Ontology:
Molecular function: protein binding; DNA-binding transcription factor activity, RNA polymerase II-specific; RNA polymerase II transcription regulatory region sequence-specific DNA binding
Biological process: regulation of transcription by RNA polymerase II; regulation of DNA-templated transcription
Cellular component: nucleus
Genetic constraint (gnomAD): Loss-of-function variants: 8 observed, 8 expected, observed/expected ratio (o/e) 1, 90% interval 0.58 to 1.72. That is too few expected variants to judge how well the gene tolerates losing a copy. Missense variants: 772 observed, 787.18 expected, observed/expected ratio (o/e) 0.98, 90% interval 0.92 to 1.04. Synonymous variants: 245 observed, 254.59 expected, observed/expected ratio (o/e) 0.96, 90% interval 0.87 to 1.07.
Homologues: Paralogues in human: ZNF433 (43% identical), ZNF700 (40% identical), ZNF443 (39% identical), ZNF799 (37% identical), ZNF709 (37% identical), ZNF823 (36% identical), ZNF44 (35% identical), ZNF791 (34% identical), ZNF441 (34% identical), ZNF442 (34% identical), ZNF563 (34% identical), ZNF878 (34% identical), and 3 more.
Diseases named in the same sentence as ZNF844 in open-access papers:
ZNF844 is named in the same sentence as 1 disease in open-access papers, as found by Europe PMC text mining. Sharing a sentence is not in itself a finding about the gene and the disease. The quoted sentences say what the papers report.
tumor (1 paper, 2025). "ZNF844 is closely related to immune-associated pathways and the tumor microenvironment, and may play a critical role in immune evasion and T cell regulation in ccRCC." (PMID 40636694, 2025). "Previous studies have shown that ZNF844, a paralog of ZNF433, is also significantly downregulated in KIRC and is associated with poorer survival, advanced pathological stage, and higher tumor grade, suggesting its potential role as a tumor suppressor." (PMID 40636694, 2025).